IL6 (interleukin 6)
Diseases named in the same sentence as IL6 in open-access papers (continued):
Sharing a sentence is not in itself a finding about the gene and the disease.
prostate carcinoma (continued). "Paracrine action of IL‐6 inhibits the proliferation and induces cell differentiation of prostate cancer cells, whilst autocrine action stimulates the growth of prostate cancer cells." (PMID 36524848, 2023). "In a basic study on prostate cancer, IL-6 was found to be highly expressed in androgen-resistant prostate cancer cell lines (DU145, PC3) and hardly expressed in androgen-dependent prostate cancer cells (LNCaP)." (PMID 37576403, 2023). "It is well-established that IL6 is an essential chemokine for the recruitment of macrophages in cancers, such as cervical cancer and prostate cancer." (PMID 37454220, 2023). "Prostate cancer cells become resistant to enzalutamide by producing IL-6, which leads to the activation of STAT3." (PMID 37576403, 2023). "The authors conclude that the cytokines IL-1α, IL-1β, IL-6, and IL-8 have a significant role in prostate cancer development." (PMID 37048115, 2023). "In another study, significant differences between prostate cancer patients and controls were found for IL-6 in the serum samples of 79 men." (PMID 36733309, 2023). "Inhibition of IL-6 has a role in prostate cancer growth and prostate prevention with high specificity." (PMID 36903908, 2023). "Previous studies have demonstrated that the IL-6 gene expression is activated by tumor-producing TGFβ in many cell types, including human prostate cancer cells, fibroblasts, osteoblasts, and retinal pigmented epithelial cells." (PMID 37511415, 2023). "Previous studies have reported that the levels of IL-6 were higher in patients with prostate cancer." (PMID 36733309, 2023). "Mechanistically, CHD1 is stable in PTEN-null prostate cancer cells and interacts with the active epigenetic marker trimethylation of H3K4me3 in the IL-6 gene." (PMID 37190171, 2023). "In this study, we aimed to elucidate the effect of IL-6 on cancer stemness genes in prostate cancer cells." (PMID 37987305, 2023). "We demonstrated the efficacy of ZQD treatment in reducing prostate cancer cells proliferation and tumor growth, evidenced by inhibiting the activation of IL-6/STAT3 signaling pathway in vitro (PC3 and DU145 cells) and xenograft tumor model in vivo." (PMID 37576403, 2023). "NF-κB signaling pathway induces IL-6 expression, which plays an essential role in prostate cancer progression, the development of CRPC, and enzalutamide resistance." (PMID 36982155, 2023). "Macrophages stimulate IL-6 produced by tumor cells and promote progressive growth of bone metastasis of prostate cancer through their positive feedback." (PMID 37151385, 2023). "Studies have also confirmed that IL-6 increases significantly in prostate cancer tissue, where it plays the role of a growth factor for cells." (PMID 37847180, 2023). "It should be noted that although IL-6 has been targeted for its proliferative and antiapoptotic effects, variable IL-6 responses have been observed in prostate cancer." (PMID 37958367, 2023). "Bone morphogenetic protein (BMP)-6 released by prostate cancer cells stimulates M2-type-TAMs to produce IL-6, while tumor-infiltrating M2-type-TAMs promote NED development by activating downstream IL-6 signaling." (PMID 37142586, 2023). "Endogenous IL-6 was identified as a resistant factor for some chemotherapeutic agents, such as etoposide and cis-diamminedichloroplatinum, in prostate carcinoma cells." (PMID 37511415, 2023). "High-fat diets can induce localized inflammation in the prostate gland, promoting prostate cancer growth by suppressing the tumor immune response, potentially through the IL-6 and STAT3 signaling pathway." (PMID 38140390, 2023). "IL6/IL6RA signaling plays an important role in the progression of various cancers including prostate cancers." (PMID 35689758, 2023). "For instance, IL-6 secretion by CAFs has been shown to facilitate angiogenesis in vitro through the stimulation of VEGF secretion by prostate cancer cells, which is also known to facilitate ADT resistance." (PMID 36671452, 2022).
prostate carcinoma (continued). "For example, in cell line models of prostate cancer, overexpression of IL6 enhances cellular proliferation, tumor progression, and neuroendocrine differentiation." (PMID 35911788, 2022). "In prostate cancer cell lines (LNCap DuCaP and VCaP), galiellalactone strongly repressed IL-6-induced activity of the androgen receptor (AR; e.g., PSA expression)." (PMID 36429126, 2022). "In prostate cancer, we have shown the inhibitory effects of orally administered resveratrol, trimethoxy-resveratrol, and piceatannol on circulating IL-6 levels in LNCaP xenografts." (PMID 36551523, 2022). "In the TRAMP genetic mouse model of prostate cancer, epithelial deletion of IL6 functions delays progression." (PMID 35911788, 2022). "The IL-6 serum levels were significantly increased in patients with prostate cancer after the 25th radiotherapy fraction in comparison with those levels determined before radiotherapy." (PMID 36368974, 2022). "IL-6 has been reported to increase erythrocyte sedimentation rate, which was proved to be a prognostic factor in the survival of advanced prostate cancer patients." (PMID 36140220, 2022). "In line with this, activation of STAT3, the downstream mediator of IL-6 signal transduction, was elevated by coculture of prostate cancer cells with bone marrow stromal cells, and subsequently reduced following IL-6 blockade." (PMID 35213227, 2022). "In cancers such as prostate cancer and liver cancer, the activation of the classic IL6 signaling pathway is generally accompanied by tumor progression, which can be reversed by inhibition of the IL6/JAK/STATS pathway." (PMID 35692503, 2022). "Stromal IL6 signaling has been shown to alter hormone metabolism in ER-negative breast cancers and crosstalk between estrogen and IL6 signaling in the tumor microenvironment has been reported in prostate cancer cell lines." (PMID 36230597, 2022). "Taken together, simulated μg induced 3D growth of PC-3 cancer cells combined with a differential expression of the cytokines IL-1α, IL-1β, IL-6 and IL-8, supporting their involvement in growth and progression of prostate cancer cells." (PMID 35252204, 2022). "In agreement with our results, some trials have demonstrated an enhanced NK cytotoxic response after the silencing of IL-6 in prostate cancer cells." (PMID 35465350, 2022). "IL-10 was confirmed to be highly expressed in various types of cancer, including ovarian cancer, lymphoma, prostate cancer, and GC, which can downregulate the inflammatory cytokines IL-6 and IL-8." (PMID 35572666, 2022). "Collectively, these results showed that QL serum resensitized paclitaxel-resistant prostate cancer cells to paclitaxel via IL-6/STAT3 signaling in TAMs." (PMID 35193986, 2022). "Regulation of IL-6 synthesis and secretion in prostate cancer is the result of several cellular processes, some of which being interconnected." (PMID 35464825, 2022). "In patients with prostate cancer treated with radiotherapy serum levels of IL-6 and TGF-β1 were measured before the start of radiotherapy and after the 25th radiotherapy fraction." (PMID 36368974, 2022). "Serum concentrations of IL-6 and sIL-6R were correlated with advanced stages of the disease and a poor prognosis in prostate cancer patients." (PMID 35464825, 2022). "DIO-induced inflammation accelerated prostate cancer growth via IL6 secreted by prostatic macrophages, as well phosphorylated STAT3- (pSTAT3-) positive tumor cells." (PMID 35478937, 2022). "IL-6 serum levels were significantly increased in patients with prostate cancer after the 25th radiotherapy fraction in comparison with those levels determined before radiotherapy (p < 0.001)." (PMID 36368974, 2022). "Actually, CXCL13 was found to be positively correlated with IL-6 in prostate cancer, BPH and high-grade prostatic intraepithelial neoplasia, and involved in experimental autoimmune cystitis and interstitial cystitis." (PMID 36613500, 2022).
prostate carcinoma (continued). "Heidarian examined the dose‐dependent effects of carvacrol in human prostate cancer cell lines, which significantly reduced IL‐6 gene expression as compared to the control group in which IL‐6 protein reduced 41.5% and 52.7% at 360 and 420 μM." (PMID 36348778, 2022). "Macrophage inhibitory cytokine‐1 (MIC-1) production is augmented in prostate cancer cells by adipocytes-mediated lipolysis and fatty acid release, which enforces the secretion of IL-6 and IL-8 from periprostatic CAFs for M2-polarization." (PMID 36117852, 2022). "We treated TAMs with QL-serum together with interleukin (IL)-6, measured the expression of M1 and M2 markers, and the viability of paclitaxel resistant prostate cancer cells." (PMID 35193986, 2022). "The expression of IL-6 and IL-6R in prostate cancer, as well as the role of IL-6 as a growth factor in prostate cancer, was well documented." (PMID 35464825, 2022). "In contrast, the silencing of androgen receptor expression enhances CSC-like traits in prostate cancer via IL-6/STAT3 signaling." (PMID 36010693, 2022). "IL6 for example exhibits a higher expression in PC-3 cells as well as in other prostate cancer cell lines and plays a major role as a proliferative autocrine and paracrine factor in prostate cancer." (PMID 35252204, 2022). "First, IL-6 levels in serum are increased in patients with prostate cancer, and it significantly correlated with cancer prognosis." (PMID 36140220, 2022). "Interleukin-6 (IL-6) has been established as a driver of prostate carcinogenesis and tumor progression while less is known about the role of ciliary neurotrophic factor (CNTF), a member of the IL-6 cytokine family in prostate cancer." (PMID 36497399, 2022). "In support of previous studies, IL-6 was found to be strongly expressed in HS5 bone marrow stromal cells as compared to HS27a bone marrow stromal cells or prostate cancer cell lines." (PMID 35213227, 2022). "Overexpression of IL-6 and its receptors were usually found in BC, prostate cancer, and oral squamous cell carcinoma." (PMID 35211500, 2022). "In human prostate cancer, IL-6 secretion was restricted to the prostatic stromal component, whereas IL-6 was derived mainly by local macrophages upon HFD stimulation." (PMID 36117852, 2022). "Increased systemic inflammation with activation of the IL6-STAT pathway was seen in prostate cancer patients with pelvic inflammation." (PMID 35681714, 2022). "IL-6 accelerates cancer cell proliferation and survival, which influence the progression and metastasis of prostate cancer." (PMID 36140220, 2022). "A clinical study from Nakashima’s team measured IL-6 levels in serum samples from stages B, C, and D prostate cancer patients." (PMID 36140220, 2022). "Gram-negative bacterial cell wall component, LPS, is recognized by TLR4, and activation of TLR4 promotes prostate cancer development and induces nitric oxide and IL-6 production in CRC." (PMID 36003378, 2022). "Though, increased IL-6 promoted the development of benign prostatic hyperplasia and prostate cancer." (PMID 35464825, 2022). "NF-κB activation in prostate cancer cell lines leads to the increased production of IL-6, which contributes to docetaxel resistance." (PMID 36010693, 2022). "Interleukin 6 (IL-6) in prostate cancer (PCa) is recognized as a potential mediator and biomarker of disease progression." (PMID 36371231, 2022). "However, it is possible that the association of IL-6 with prostate cancer risk could be modified by BMI, as increasing IL-6 was positively associated with prostate cancer in normal-weight subjects, but inversely associated with prostate cancer in overweight/obese men." (PMID 34681797, 2021). "As an example, IL-6 is known for playing a part in chemoresistance and metastasis of aggressive prostate cancer." (PMID 34625047, 2021). "Upon macrophage activation, fibroblasts stimulate prostatic cancer with the involvement of IL-6 and stromal cell-derived factor-1 (SDF-1)." (PMID 34680425, 2021).
prostate carcinoma (continued). "IL-6 has been shown to promote androgen-dependent prostate cancer cell proliferation under low-androgen conditions in vitro and in castrated mice, accompanied by PSA gene expression." (PMID 34295814, 2021). "For anti-IL-6 clinical trials in prostate cancer, it is important to appropriately approach individual patients." (PMID 34204596, 2021). "The study also showed that periprostatic adipose tissue derived IL-6 correlated with pathological grade of prostate cancer and there was greater phosphorylation on STAT3 with high grade tumors." (PMID 33920379, 2021). "Since IL-6 and its receptor are expressed in prostate cancer tissue and in the microenvironment, the effects of the cytokine were investigated in cellular and animal models." (PMID 34204596, 2021). "Compared with men with normal prostates, benign prostatic hyperplasia, prostatitis and localized disease, approximately 50% of patients with advanced prostate cancer have increased levels of serum IL-6." (PMID 34630112, 2021). "Ligand-independent and synergistic activation of the AR by IL-6 is an important mechanism that contributes to prostate cancer progression." (PMID 34204596, 2021). "IL-6 can promote the proliferation of prostate cancer and inhibit apoptosis via the JAK/STAT pathway through the extracellular signal-regulated kinase 1 and 2 (ERK1/2)-mitogen activated protein kinase (MAPK) pathway, and the PI3K pathway." (PMID 33920379, 2021). "CAFs isolated from prostate cancer and intrahepatic cholangiocarcinoma were also shown to highly secrete IL-6." (PMID 34047814, 2021). "Cytokines (IL-6 and IL-8) have been reported to stimulate prostate cancer cell proliferation in an autocrine and paracrine manner, as well as to inhibit apoptotic pathways." (PMID 33673284, 2021). "To further support these results, we measured the expression of IL-6 and PSA in prostate cancer tissues by IHC and analyzed the relationship between the expression levels of IRE1α, IL-6 and PSA." (PMID 34295814, 2021). "The role of REST in NEPC has been further supported through its ability to suppress interleukin-6 induced neuroendocrine differentiation in prostate cancer cells." (PMID 33572108, 2021). "A recent in vitro study showed that Chlamydia trachomatis can proliferate in prostate cancer cells, resulting in enhanced transcription of IL-6 and FGF-2 genes, while FGF-2 can promote vascularization and metastasis of primary prostate cancer." (PMID 34956913, 2021). "Elevated levels of IL-6 are observed in a large number of patients with solid tumors including prostate cancer, and IL6 stimulates the activation of STAT3 signaling pathway, which is often associated with poor patient outcomes." (PMID 34684783, 2021). "All those results indicated that IRE1α promotes the progression of prostate cancer in an IRE1α-IL-6-AR-positive feedback loop manner." (PMID 34295814, 2021). "An example is in prostate cancer, where upregulated GCN5 downregulates Egr-1 expression via the PI3K/PTEN/Akt signaling pathway, negatively affecting IL-6-induced prostate cancer cell metastasis and epithelial-mesenchymal transition (EMT)." (PMID 34880761, 2021). "The previous findings were in consistent with Kassi and his colleagues, where monoterpene, a special phenolic component in thyme honey, had shown an apoptotic activity mediated by suppressing NF-κB activity and IL-6 secretion in prostate cancer cell line." (PMID 33441127, 2021). "An important area of research in prostate cancer is the interaction between signaling pathways of IL-6 and AR." (PMID 34204596, 2021). "TQ has suppressed prostate cancer’s carcinogenesis at 45 μM by reducing IL-6 expression and inhibiting the phosphorylation of STAT3, AKT, and extracellular signal-regulated kinase (ERK) proteins in PC3 prostate cancer cells." (PMID 33923474, 2021).
prostate carcinoma (continued). "The role of IL6 and other cytokines in driving prostate cancer progression have been demonstrated by studies with cell lines and mouse models." (PMID 34638448, 2021). "High levels of IL6 in several cancer cells, such as prostate cancer, ovarian cancer, and renal cell carcinoma, resulted in poor prognosis in cancer patients." (PMID 33714953, 2021). "Pharmacologic inhibition of IL6 in combination with ICB elicits robust antitumor responses in prostate cancer." (PMID 35003065, 2021). "In summary, CK increased cytotoxicity without hurting normal cells, sub G1 population, cleaved PARP and decreased the expression of pro-caspase-3, VEGF, TGF-β, IL-6, IL-10, Cyclin D1, c-Myc and Bcl-xL in prostate cancer cells." (PMID 34440920, 2021). "We have previously shown that the STAT3 inhibitor galiellalactone inhibits cytokines such as GM-CSF and IL8 from prostate cancer cells and IL1ß, IL6 and IL10 secretion from monocytes." (PMID 33786638, 2021). "In contrast, the addition of IL-6 or transiently transfected with an overexpression plasmid for AR significantly restored prostate cancer cell proliferation and colony formation, which was reduced by knockdown of IRE1α in C4-2B cells." (PMID 34295814, 2021). "The expression of IL-6 and its receptor were investigated in radical prostatectomy specimens from prostate cancer patients." (PMID 33920379, 2021). "bFGF, along with interleukin-6 (IL-6) are known contributors of androgen ablation, chemotherapy resistance and metastatic dissemination of prostate cancer cells." (PMID 33804681, 2021). "On the other hand, IL-6 has been up-regulated in different types of malignancy but using serial concentrations of Arabic honey reduce the levels of IL-6 in prostate cancer cell line." (PMID 33441127, 2021). "IL-6-triggered JAK-STAT3 signaling pathway upregulated PD-L1 expression in prostate cancer, which IL-6-expressing tumor is resistant to NK cell-mediated immune action." (PMID 34088360, 2021). "IL6 expression is necessary for cell proliferation in prostate cancer, and AGP inhibits both mRNA and protein expression of IL6 that further induces apoptotic cell death." (PMID 34795581, 2021). "Our data indicated that IRE1α, IL-6 and AR formed a positive feedback loop, and through which facilitated prostate cancer cell proliferation under androgen deprivation conditions." (PMID 34295814, 2021). "Among the currently known growth signals, insulin-like growth factor (IGF)-1 and IL-6 have been previously studied for their roles in prostate cancer." (PMID 34682865, 2021). "Elevated levels of IL-6 and IL-8 are associated with paracrine secretion in the SASP phenotype, and vitamin D3 has been proven to exert anti-inflammatory effects in prostate cancer through the inhibition of IL-6, IL-8, and TNF-α." (PMID 33928081, 2021). "Consistently, the activity of the IL-6/STAT3 signaling pathway is proportional to the growth rate of advanced prostate cancer." (PMID 33535458, 2021). "Prostate cancer patients with higher IRE1α expression also had a higher IL-6 or PSA expression, and vice versa." (PMID 34295814, 2021). "In prostate cancer, it is important to analyze IL-6 signaling in the context of coexpression with ERG." (PMID 34204596, 2021). "The expression of Rictor, phosphorylation of Rictor (Thr-1135), AKT (Ser-473) and PKCα (Ser-657) were all increased after IGF-1 and IL-6 treatment in both prostate cancer cell lines and in RWPE1 cells." (PMID 34682865, 2021). "One of the reasons for scientific interest in IL-6 in prostate cancer is its involvement in cellular plasticity." (PMID 34204596, 2021). "It has been reported that TGF-β activates IL6 expression in prostate cancer cells through the Smad or NF-κB signaling pathways." (PMID 33576874, 2021). "There also are other endogenous inhibitors of expression of IL-6 in prostate cancer, such as Sprouty2." (PMID 34204596, 2021).